STAT3 (signal transducer and activator of transcription 3)
Diseases named in the same sentence as STAT3 in open-access papers (continued):
Sharing a sentence is not in itself a finding about the gene and the disease.
colitis (continued). "Reassuringly, IL-10 serum levels and their expressions in T cells were restored in colitis mice when they underwent late onset tofacitinib treatment although tofacitinib had been shown to completely abolish the expression of this STAT3-dependent cytokine in culture." (PMID 37275854, 2023). "Results in the present study confirmed that XJS might mitigate CD-like experimental colitis through inhibiting ferroptosis in IECs via downregulation of FGL1/NF-κB/STAT3 positive feedback loop signals." (PMID 37153794, 2023). "Furthermore, signal transducer and activator of transcription 3 (STAT3) and NF-κβ signaling in IECs are also relevant since defects in these two pathways favor the formation of colitis." (PMID 36837862, 2023). "The anti-colitis mechanisms of Eckol might be attributed to the down-regulation of the TLR4/NF-κB/STAT3 pathway, inhibition of inflammation and apoptosis, as well as its immunoregulatory activity." (PMID 37504907, 2023). "However, the protective effects of FGF21 KO against DSS-induced colitis and the colonic phosphorylation of STAT3 cannot be explained by the IL-6 regulation since IL-6 expression was reduced in the KO mice." (PMID 37432218, 2023). "However, Bp7 and Bp8 intervention drastically down-regulated the expression of Tlr4, NF-κB, iNOS, and COX2 and drastically up-regulated the expression of STAT3, Nrf2, and PPARγ in colitis mice (p < 0.05)." (PMID 35681301, 2022). "In conclusion, we herein demonstrated that TSC1-mTOR signaling pathway negatively regulated Th1/Th17-type cytokine expression in LPS-stimulated macrophages and exacerbated pathogenesis of colitis in mice via reprogramming metabolism and STAT3-RORγT/T-bet pathway." (PMID 36465179, 2022). "In addition, conditional knockout of STAT3 in hematopoietic cells was found to result in the induction of colitis in mice due to chronic gut inflammation." (PMID 36359827, 2022). "Bp7 and Bp8 intervention elevated the expression of STAT3 and PPARγ in colitis mice." (PMID 35681301, 2022). "Together, these data revealed that PAMK treatment alleviated DSS-induced colitis by regulating the Th17/Treg cell balance, which may be dependent on the inhibition of the IL-6/STAT3 signaling pathway." (PMID 36341374, 2022). "Baicalein has also been reported to ameliorate dextran sulfate sodium-induced colitis by inhibiting NF-κB and STAT3 signaling pathways and mitigating radiation-induced enteritis by improving endothelial dysfunction, thereby preventing the development of colitis-associated cancer." (PMID 35966251, 2022). "Mice with a STAT3 deletion in FOXP3+ Treg cells could develop aggressive colitis owing to uncontrolled TH17 responses." (PMID 36532769, 2022). "This implied that mmu_circ_0001109 might link with the colitis through the Jak‐STAT3 or NF‐kappa B signalling pathway." (PMID 35184406, 2022). "Our RNA-seq data show that colitis activated whereas BBR suppressed Jak-Stat3 signaling, a critical regulator of cytokine expression and inflammation, consistent with previous studies showing that Stat3 activation might be affected by BBR." (PMID 36528592, 2022). "Overactivation of NF-κB and STAT3 was observed in colitis mice, which agrees with previous studies." (PMID 36079868, 2022). "The activation of IL-6/STAT3 pathway is involved in the occurrence and development of colitis." (PMID 35982893, 2022). "In mice, MRS2211 treatment similarly inhibited the phosphorylation of STAT3 in DSS-induced colitis." (PMID 35982893, 2022). "STAT3 expression is decreased by 0.03-fold in the colitis group." (PMID 35832050, 2022). "Hence, above observations determine that MIR31 regulates inflammatory response through suppressing p65 and STAT3 activation, but promoting the recovery of epithelia during colitis." (PMID 36590397, 2022). "In addition, we found that the effect of P2Y13 on colitis is related to the activation of the IL-6/STAT3 pathway." (PMID 35982893, 2022).
colitis (continued). "Our results suggested that PAMK treatment regulated the Th17/Treg cell balance to attenuate DSS-induced colitis in mice, which may be dependent on the inhibition of the IL-6/STAT3 signaling pathway." (PMID 36341374, 2022). "STAT3 activation in intestinal epithelial cells is essential for mucosal wound healing through its ability to regenerate epithelium, thereby playing an integral role in recovery from colitis." (PMID 35832050, 2022). "Our subsequent data in vivo and in vitro confirmed that mmu_circ_0001109 could exacerbate the colitis by up‐regulating the Jak‐STAT3 and NF‐kappa B signalling pathways, and mmu_circ_0001845 promoted the CAC transformation through the Wnt signalling pathway." (PMID 35184406, 2022). "Our results showed that the regulatory effect of PAMK on the Th17/Treg balance in colitis may depend on the inhibition of the IL-6/STAT3 pathway." (PMID 36341374, 2022). "In particular, a recent study demonstrated that AC treatment ameliorated the severity of trinitrozobenzoic acid (TNBS)-induced colitis by inhibiting reactive oxygen species (ROS) generation and downregulating pro-inflammatory signaling pathways such as STAT3/MAPK/NF-κB." (PMID 36286060, 2022). "In addition, it was found that miR-214-3p targets the STAT6 gene to regulate colitis, and both STAT3 and STAT6 belong to the same STAT family." (PMID 35743265, 2022). "Moreover, a T cell-specific deletion of Stat3 had been shown to diminish the severity of DSS-colitis, consistent with our observation that increased Stat3 activity in CD5 KD T cells in turn exacerbates gut inflammation in this model." (PMID 35720357, 2022). "However, further studies on signaling pathways involved in chronic inflammation-induced CRC, such as MAPK, IL-6/STAT3, COX-2/PGE2, and IL-23/Th17, are necessary to investigate the protective effect of DRB in the pathogenesis of colitis-associated CRC." (PMID 36360101, 2022). "Interestingly, in the murine colitis model, we demonstrate that an increased frequency of STAT3 GOF Tregs that had downregulated Foxp3 expression became IL-17A–producing ex-Tregs." (PMID 36136607, 2022). "Applying nicotine as a treatment agent could ameliorate UC symptoms through upregulation of miR-124 expression by blocking STAT3 activation in DSS-induced colitis mice and epithelial cells." (PMID 33921348, 2021). "Furthermore, when mouse colitis is associated with bacterial infection, USP25 can aggravate colitis by promoting STAT3 phosphorylation, consistent with previous studies, our study found that USP25 aggravates AP by regulating STAT3 (especially p-STAT3)." (PMID 35096833, 2021). "In addition, downregulation of STAT3 has been shown to improve disease severity in a murine model of colitis." (PMID 34068714, 2021). "Hence, the reduction in STAT3 activity in both mouse models significantly compromised intestinal barrier function in the context of colitis." (PMID 33673239, 2021). "However, studies had shown that Faecalitalea was significantly increased in DSS-induced colitis rat models, and Erysipelotrichaceae, the family including this genus, was believed to be a trigger of the NF-κB and STAT3 pathways in colitis." (PMID 34053449, 2021). "In conclusion, melatonin-mediated MT2 weakened GR feedback, suppressed oxidative stress, restored the intestinal microbiota and its metabolites homeostasis, and inactivated the STAT3/AP-1/NF-κB pathway-induced inflammatory response, further improving SD-induced colitis." (PMID 34257825, 2021). "The reduction in the capacity of the IL-6ST/gp130 receptor to activate STAT1 and STAT3 in our heterozygous GP130∆STAT/+ mice demonstrates that IL-6ST/gp130 receptor signalling is required for the maintenance of intestinal barrier function during colitis." (PMID 33673239, 2021).
colitis (continued). "One of the molecular mechanisms in which ETBF triggers colitis and induces colon tumorigenesis in multiple intestinal neoplasia (Min) mice, is via the activation of signal transducer and activator of transcription 3 (STAT3) and induction of T-helper type-17 (TH17) T cell responses." (PMID 34225577, 2021). "We hypothesised that systemic reduction in STAT3 activity would exacerbate the development of acute colitis injury through the modulation of intestinal barrier integrity." (PMID 33673239, 2021). "In case of UTTR1147A, efficient STAT3 activation via the IL-22 receptor could be demonstrated in vitro, resulting in protective in vivo effects in a murine colitis model." (PMID 33869257, 2021). "Similarly, mice with conditional deletion of Stat3, in IECs specifically, display increased susceptibility to both dextran sulfate sodium- (DSS) and Citrobacter rodentium-induced colitis." (PMID 33673239, 2021). "Our current findings firstly suggested that PF-04447943 attenuates the DSS-induced colitis by suppressing oxidative stress, inflammation, inflammasome and the Treg/Th17 cells balance, and the mechanisms involved in regulating NF-kB, STAT3, Nrf2, and MAPK (ERK) pathway." (PMID 33967779, 2021). "Using a mouse model of Th2-mediated colitis, IL-22 gene delivery could induce expression of mucus components and goblet cells in a STAT3-dependent manner, which resulted in increased mucus production and thus less severe colitis." (PMID 33869257, 2021). "Thus, the profound induction of Reg3b and Reg3g in GP130ΔSTAT/+ mice strongly implicates that IL-6ST/gp130/STAT3 signalling contributes to the regulation of host microbiome composition during colitis." (PMID 33673239, 2021). "Interestingly, although Prkar2a−/− mice exhibited an ameliorated DSS-induced colitis, STAT3 activation decreased in Prkar2a−/− mice than in WT mice during acute colitis." (PMID 34349238, 2021). "Oroxylin A also decreased STAT3 activity to suppress colitis-stimulated carcinogenesis." (PMID 34068421, 2021). "However, the significance as well as the cellular mechanisms by which IL-6ST/gp130/STAT3 signalling promote barrier integrity during DSS-induced colitis are yet to be elucidated." (PMID 33673239, 2021). "As STAT3 activation was suppressed in Prkar2a−/− mice and PKA was activated before STAT3 during colitis, we hypothesized that PRKAR2A might influence experimental colitis by modulating STAT3 signaling." (PMID 34349238, 2021). "Interestingly, mice with Stat3 ablation in macrophages and neutrophils develop spontaneous enterocolitis, whereas T-cell specific Stat3 deletion offers protection against inflammation in a T-cell transfer model of colitis." (PMID 33673239, 2021). "As well, STAT3 activation in T-cells directly contributes to colitis." (PMID 32411289, 2020). "ETBF rapidly induced the exclusive activation of signal transducer and activator of transcription-3 (STAT3) with colitis characterized by T helper 17 (Th17) responses, which might promote cancer in cooperation with the modified colonic epithelium." (PMID 33329610, 2020). "Through Western bolting assay, we verified the key proteins in the Bcl-6/Blimp-1 signaling pathway and found that SSP significantly inhibited expression of Bcl-6, STAT3, and p-STAT3 proteins and improved expression of Blimp-1 in colonic tissues of colitis mice." (PMID 32581849, 2020). "However, when ETBF colonises a particular site of the colon, it produces a large amount of BFT damaging the intestinal mucosa to initiate ETBF-triggered colitis with the activation of the STAT3 pathway." (PMID 32863742, 2020). "In contrast, nicotine may protect against colitis by mechanisms involving micro RNA-124 and STAT3 in mice." (PMID 32614903, 2020). "Moreover, STAT3 plays important roles in the regulation of signaling between cytokines and their receptors in the pathway to colitis." (PMID 32369982, 2020).
colitis (continued). "Western blot analysis of colon tissues revealed that cyclooxygenase-2, tumor necrosis factor alpha (TNF-α), and phosphorylated signal transducer and activator of transcription-3 (p-STAT3) were significantly decreased in the colitis + 5-ASA group, whereas forkhead box P3 (FOXP3) was increased." (PMID 33092149, 2020). "Hence, our findings reveal that the anti-inflammatory properties of CEE, involving the downregulation of the expression of pro-inflammatory mediators by inactivating NF-κB and STAT3 in DSS-induced colitis mice." (PMID 32059355, 2020). "Therefore, the activation of IL-6/JAK2/STAT3 pathway is closely related to inhibit the occurrence and development of colitis, which is consistent with the expected results." (PMID 32081954, 2020). "In summary, we demonstrated that modified PD could inhibit the increased inflammatory response and reduce the severity of colitis lesions through IL-6/STAT3 signaling pathway." (PMID 32517784, 2020). "Also, in DSS-induced colitis, IL-22 has been shown to ameliorate the histological score in an STAT3-dependent manner." (PMID 32670290, 2020). "Through IL-6/STAT3 signaling pathway, modified PD could inhibit the increased inflammatory response and reduce the severity of colitis lesions." (PMID 32517784, 2020). "In the colitis model, inhibition of STAT3 and RelA expression could ameliorate colonic inflammatory damage by down‐regulating pro‐inflammatory cytokines." (PMID 32815642, 2020). "We next determined whether tRXRα expression impacted the activation of STAT3 in the acute DSS-induced colitis model that uses a single 5-day course of DSS." (PMID 30931933, 2019). "Our findings revealed that EEP suppressed protein expression levels of inducible pro-inflammatory enzymes (COX-2 and iNOS) and mRNA expression levels of cytokines (IL-6, IL-1β, and TNF-α) due to inhibitory effects of EEP on phosphorylation of NF-κB and STAT3 in DSS-induced colitis mice." (PMID 30621304, 2019). "EHLJ7 may induce intestinal flora to overexpress SCFA, especially butyric acid and then inhibit colitis inflammation through inhibition of JAK2/STAT3/SOCS1 pathway." (PMID 32038241, 2019). "STAT3 could be activated in acute DSS-induced colitis, protecting DSS-induced colonic epithelium injury." (PMID 30931933, 2019). "Our data suggested that due to increased initial IEC death a more severe inflammatory response during the DSS-induced colitis led to an upregulation of Stat3-activating cytokines, which promoted tumor growth and compensated the loss of initiated epithelial cells." (PMID 30353167, 2019). "DSS-induced mucosal inflammation or colitis was markedly increased in both IL-6-deficient mice and in mice lacking STAT3 in intestinal epithelial cells." (PMID 31798539, 2019). "In contrast, STAT3 activation in T-cells contributes to colitis." (PMID 30081609, 2018). "We have previously shown that the CHGA-derived peptide, catestatin (CST; (hCHGA352–372), protects against the development of acute intestinal inflammation in two murine models of experimental colitis through modulation of pro-inflammatory macrophages function via a STAT3-dependent mechanism." (PMID 30241336, 2018). "Thus, our findings suggest that Myo1F enhances activation of Akt and STAT3 signaling in colonic macrophages during colitis." (PMID 30687322, 2018). "NF-κB and STAT3 are two key signaling proteins related to colitis." (PMID 29724065, 2018). "Furthermore, deficiency of TRIM27 significantly impairs STAT3 activation, suppresses dextran sulfate sodium (DSS)-induced colitis, and azoxymethane (AOM)/DSS-induced CAC development in mice." (PMID 30143645, 2018). "This study illustrates the role of the S1P/S1PR1/STAT3 axis in the regulation of colitis." (PMID 29333002, 2017). "STAT3 was highly activated in DSS-induced colitis, IBD, and various tumors." (PMID 28852270, 2017).
colitis (continued). "This review aims to elucidate the role of chronic inflammation in colitis-associated CRC with a review regarding the contribution of inflammatory signaling pathways, including nuclear factor kappa B (NF-κB), IL-6/STAT3, cyclooxygenase-2 (COX-2)/PGE2, and IL-23/Th17." (PMID 28852270, 2017). "In addition, SPL appears to regulate S1P/STAT3 signaling in the context of intestinal inflammation, colitis, and the development of CAC." (PMID 29333002, 2017). "Mice with myeloid-specific STAT3-deficiencywere not protected from DSS-induced colitis, which was associated with impairedexpansion of mucosal MDSCs and reduced production of anti-inflammatory cytokines." (PMID 26848037, 2016). "We hypothesized that Grim19 would ameliorate DSS induced colitis by altering STAT3 activity and intestinal inflammation." (PMID 27258062, 2016). "Since STAT3 is inhibited by oral JAK inhibitors, STAT3 inhibitors may also be useful for DSS induced colitis treatment." (PMID 27258062, 2016). "Since FNDC4 mainly targets macrophages, STAT3 activation may have contributed to the attenuation of colitis symptoms in the FNDC4-treated mice." (PMID 27066907, 2016). "STAT3 is also involved in the pathogenesis of DSS induced colitis." (PMID 27258062, 2016). "STAT3 plays an important role in the pathogenesis of DSS induced colitis." (PMID 27258062, 2016). "Thus, inhibition of STAT3 attenuates DSS induced colitis severity by reducing proinflammatory cytokine levels during inflammation of the colon." (PMID 27258062, 2016). "In this study, we hypothesized that STAT3 inhibition can reduce colitis severity because colitis is chronic inflammatory disease and observed that STAT3 inhibition mediated by Grim19 improved acute colitis." (PMID 27258062, 2016). "Thus, it is conceivable that the protectionof gp130757F/F mice from acute DSS-induced colitis is viamyeloid-specific STAT3 activation and expansion of immunosuppressive ARG1-expressingG-MDSC subsets in the colon." (PMID 26848037, 2016). "Therefore, this indicates that Shp-2IEC-KO mice develop colitis despite the rapid and persistent activation of STAT3 and NFκB in IECs." (PMID 27582544, 2016). "Indeed, metformin exhibited a therapeutic effect by decreasing STAT3 activation in mice with DSS induced colitis." (PMID 27258062, 2016). "In this study, we demonstrate that the resistance to chemically induced colitis inmice with altered gp130 signalling is via myeloid-cell specific STAT3 activation,subsequent expansion of granulocytic MDSC in the colon and increased production ofsuppressive and protective mediators." (PMID 26848037, 2016). "This study aimed to determine whether GRIM19 reduces the expression of STAT3 and proinflammatory cytokines during the colonic inflammatory response in DSS induced colitis, and to explain the underlying mechanism." (PMID 27258062, 2016). "Moreover, disruption of STAT3 in bone marrow cells resulted in a CD-like phenotype in mice prior to death, and suppression of experimental colitis by CX3C chemokine receptor 1-bearing myeloid cells was dependent on STAT3 activation by IL-10." (PMID 26938566, 2016). "But how sodium propionate inhibits STAT3 phosphorylation in colitis needs further study." (PMID 27574508, 2016). "But, STAT3 reveals an opposing function such as double edge sword in colitis." (PMID 27258062, 2016). "Consequently, OGA+/− mice exhibited increased Iκb and STAT3 phosphorylation compared with WT mice during colitis." (PMID 25915426, 2015). "Moreover, conditional knockout of STAT3 in hematopoietic cells was found to result in the induction of colitis in mice due to chronic gut inflammation." (PMID 26106386, 2015). "The therapeutic effects of heat-killed VSL#3 on colitis may due to its effects on IL-6/STAT3 pathway." (PMID 24451125, 2013).